MIPOL1 (mirror-image polydactyly 1)
Synonyms: CCDC193
Tractability: PROTAC: ubiquitination databases record sites on it.
Gene: Protein-coding gene on chromosome 14 (37,197,891 to 37,579,125, forward strand). Ensembl gene ENSG00000151338.
Subcellular location (Human Protein Atlas): Cytosol
Gene Ontology:
Molecular function: identical protein binding; protein binding
Cellular component: cytosol; nucleus
Genetic constraint (gnomAD): Loss-of-function variants: 33 observed, 30.38 expected, observed/expected ratio (o/e) 1.09, 90% interval 0.82 to 1.45. The upper end of that interval is the gene's LOEUF score, 1.45, which puts it in group 6 of 6, group 1 being the genes least tolerant of losing a copy. Missense variants: 335 observed, 343.65 expected, observed/expected ratio (o/e) 0.97, 90% interval 0.89 to 1.07. Synonymous variants: 119 observed, 119.17 expected, observed/expected ratio (o/e) 1, 90% interval 0.86 to 1.16.
Homologues: Orthologues: chimpanzee MIPOL1 (99% identical), macaque MIPOL1 (91% identical), rabbit MIPOL1 (85% identical), pig MIPOL1 (82% identical), guinea pig MIPOL1 (81% identical), dog MIPOL1 (80% identical), rat Mipol1 (71% identical), mouse Mipol1 (65% identical), tropical clawed frog mipol1 (39% identical), zebrafish mipol1 (35% identical).
Diseases named in the same sentence as MIPOL1 in open-access papers:
MIPOL1 is named in the same sentence as 14 diseases in open-access papers, as found by Europe PMC text mining. Sharing a sentence is not in itself a finding about the gene and the disease. The quoted sentences say what the papers report.
nasopharyngeal carcinoma (4 papers, 2012 to 2022). A carcinoma arising from the nasopharyngeal epithelium. "MIPOL1 was implicated as a putative tumour suppressor gene in nasopharyngeal carcinoma (NPC), where chromosome 14 loss (including the MIPOL1 locus) is common." (PMID 22311740, 2012). "MIPOL1, mirror-image polydactyly 1, is vital for CNS development and is also known to have a tumor suppressor role in nasopharyngeal cancer." (PMID 32513296, 2020). "Interestingly, MIPOL1 is reported to exhibit tumor suppressor gene properties in nasopharyngeal carcinoma." (PMID 33827048, 2021). "The MIPOL1 may induce tumor suppression in nasopharyngeal carcinoma resulting anticancer effect." (PMID 35922788, 2022).
prostate carcinoma (3 papers, 2015 to 2020). A carcinoma that arises from epithelial cells of the prostate gland. "MIPOL1 is another androgen regulated gene that is involved in MIPOL1-ETS rearrangements in prostate cancers." (PMID 25749039, 2015). "Indeed, detection of TTC6:MIPOL1 fusion may have potential implication for prostate cancers of non-European ancestry." (PMID 30150711, 2018).
breast carcinoma (2 papers, 2020 to 2025). "The most frequently occurring fusion genes in each subtype were TTC6::MIPOL1 in HR+/HER2‒ breast cancers, LHFPL5::CLPSL1 in triple-negative breast cancer (TNBC), and TPTE2::MRPS31P2 in HER2+ breast cancers." (PMID 41213951, 2025).
bladder cancer (1 paper, 2025). "These loci included 14 previously reported bladder cancer-associated genes (eg, GSTM1 and NAT2) and 3 novel loci near MSX2, RAPGEF5, and MIPOL1 genes." (PMID 39898788, 2025).
holoprosencephaly (1 paper, 2016). Holoprosencephaly (HPE) is a complex brain malformation resulting from incomplete cleavage of the prosencephalon, occurring between the 18th and 28th day of gestation, and affecting both the forebrain and face, which results in neurological manifestations and facial anomalies of variable severity. "Biological evidence for other genes in this region also suggests possible roles in facial variation including MIPOL1, which has been observed to be affected by chromosomal aberrations in patients with craniofacial phenotypes, including holoprosencephaly." (PMID 27560520, 2016).
tumor (10 papers, 2012 to 2025). "MIPOL1 is mainly associated with body hypotrophy and tumor inhibitory." (PMID 29363554, 2018). "Mipol1, Foxa1, and Mis18bp1 are three genes associated with cell growth and tumor development." (PMID 23463770, 2013). "MIPOL1 encodes a coiled-coil domain-containing protein, which may function as a tumor suppressor." (PMID 33224264, 2020). "Nineteen genes (44%) demonstrated loss or promoter silencing of the wildtype allele in at least one tumour, with six genes (SLC12A4, LOXL2, ZCCHC4, LLGL2, MIPOL1, SCYL3) demonstrating this in multiple samples." (PMID 39794353, 2025). "The genes that have been highlighted by this analysis include mirror image polydactyly-1 (MIPOL1), a candidate tumour suppressor gene and ENPP5 (a closely-related molecule to ENPP2 (autotaxin))." (PMID 22311740, 2012). "Re-expression of MIPOL1 in NPC cell lines greatly reduced their ability to proliferate or form tumours in xenograft experiments." (PMID 22311740, 2012). "In our study MIPOL1 was found to be 2.4-fold downregulated in the higher vascularity tumours." (PMID 22311740, 2012). "MIPOL1 is thought to act as a tumor suppressor, and its fusions may accompany ETV1 fusions." (PMID 37349736, 2023). "Eight genes (CDH23, HARS2, LLGL2, LTBP1, MAP6D1, MIPOL1, SCYL3, ZNF418) showed some degree of promoter methylation in at least one tumour, but only MIPOL1 exhibited probable homozygous methylation in more than one sample." (PMID 39794353, 2025).
cancer (1 paper, 2025). A tumor composed of atypical neoplastic, often pleomorphic cells that invade other tissues. "Finally, the novel locus on chromosome 14 maps to the MIPOL1 tumor suppressor gene, previously shown to be linked to certain cancers." (PMID 39898788, 2025).
MIPOL1 also shares sentences with these, for which no sentence is quoted: colon adenocarcinoma (1 paper); metastatic prostate carcinoma (1); oral squamous cell carcinoma (1); polydactyly (1); prostate adenocarcinoma (1); rectal adenocarcinoma (1); triple-negative breast carcinoma (1).